BIK (BCL2 interacting killer)
Description:
Accelerates programmed cell death. Association to the apoptosis repressors Bcl-X(L), BHRF1, Bcl-2 or its adenovirus homolog E1B 19k protein suppresses this death-promoting activity. Does not interact with BAX.
Synonyms: NBK; BIP1; BP4
Tractability: Antibody: UniProt predicts a signal peptide or a membrane-spanning region. PROTAC: UniProt records ubiquitination sites on it; ubiquitination databases record sites on it.
Gene: Protein-coding gene on chromosome 22 (43,110,748 to 43,129,712, forward strand). Ensembl gene ENSG00000100290.
Subcellular location: Endomembrane system; Mitochondrion membrane
Gene Ontology:
Molecular function: protein binding
Biological process: positive regulation of protein-containing complex assembly; positive regulation of release of cytochrome c from mitochondria; regulation of apoptotic process; apoptotic mitochondrial changes; apoptotic process; male gonad development
Cellular component: Bcl-2 family protein complex; endomembrane system; mitochondrial membrane
Genetic constraint (gnomAD): Loss-of-function variants: 14 observed, 11.05 expected, observed/expected ratio (o/e) 1.27, 90% interval 0.83 to 1.84. The upper end of that interval is the gene's LOEUF score, 1.84, which puts it in group 6 of 6, group 1 being the genes least tolerant of losing a copy. Missense variants: 215 observed, 194.37 expected, observed/expected ratio (o/e) 1.11, 90% interval 0.99 to 1.24. Synonymous variants: 86 observed, 77.62 expected, observed/expected ratio (o/e) 1.11, 90% interval 0.93 to 1.33.
Homologues: Orthologues: chimpanzee BIK (98% identical), macaque BIK (89% identical), rat Bik (43% identical), mouse Bik (39% identical), dog BIK (38% identical).
Diseases named in the same sentence as BIK in open-access papers:
BIK is named in the same sentence as 48 diseases in open-access papers, as found by Europe PMC text mining. Sharing a sentence is not in itself a finding about the gene and the disease. The quoted sentences say what the papers report.
breast carcinoma (30 papers, 2005 to 2026). "In contrast, established breast cancer cell lines showed barely detectable levels of BIK, likely related to the fact that tumor-associated stressors are absent in cell-culture conditions." (PMID 32528057, 2020). "Here we show that BIK expression in breast cancer cell lines activates caspases and induces genomic damage through caspase-activated DNase (CAD)." (PMID 32528057, 2020). "To understand the clinical significance of high BIK levels in relation to the survival outcomes of breast cancer patients, we examined BIK mRNA levels in five publically available datasets." (PMID 32528057, 2020). "Altogether, our study provides a novel link between weak apoptotic induction and its potential to promote tumor evolution in BIK-high breast cancers." (PMID 32528057, 2020). "In human breast cancer cells, Grp78 interacts physically and functionally with BIK and inhibits apoptosis mediated by BIK." (PMID 30754624, 2019). "We have previously shown that in 3D type I collagen matrix, DDR1 triggers a BIK-mediated apoptosis in poorly invasive luminal-like breast carcinomas cell lines." (PMID 31130862, 2019). "We have previously shown that in 3D collagen matrix, DDR1 plays a key role as it promotes cell growth suppression and apoptosis through the upregulation of the pro-apoptotic mediator BIK in noninvasive luminal-like breast carcinoma cells." (PMID 31130862, 2019). "Collectively, these results suggested that Star-PAP, by regulating the expression of BIK, induces apoptosis of breast cancer cells through the mitochondrial pathway." (PMID 28151486, 2017). "BIK plays a critical role in promoting estrogen starvation or anti-estrogen-mediated cell death in human breast cancer cells, and BIK knock down impairs estrogen starvation-induced cell death in MCF7 cells." (PMID 29145850, 2017). "BIK, one of Bcl-2 homology domain 3-only proteins was identified to induce apoptosis and predict breast cancer outcomes independently." (PMID 29340021, 2017). "For example, Si X et alreported that lncRNA H19 confers chemoresistance in ERα-positive breast cancer through epigenetic silencing of the pro-apoptotic gene BIK." (PMID 29069754, 2017). "In this study, we proved that Star-PAP, by regulating expression of BIK, induces apoptosis of breast cancer cells through the mitochondrial pathway." (PMID 28151486, 2017). "In human breast cancer cells, the association between Star-PAP and BIK mRNA was firstly verified by RNA immunoprecipitation (RIP) followed by RT-PCR." (PMID 28151486, 2017). "BIK has been found to be over-expressed in 14 out of 15 breast cancer samples, and was also present in a gene expression signature consisting of 64 genes that correlated with long-term survival in non-small cell lung cancer patients." (PMID 27902785, 2016). "Another gene BIK, an apoptotic inducer in breast cancer cell, also known as BCL2 interacting killer performs its activity primarily at another intracellular sub-location, the endoplasmic reticulum (C12)." (PMID 24997799, 2014). "We showed that pro-apoptotic BCL2-interacting killer gene (BIK/NBK) overexpressed in nearly all samples (14/15), which makes it a possible candidate for further studies on its role in breast cancer." (PMID 16060964, 2005). "Computational modeling following induction of ER stress by antiestrogens in breast cancer cells identified several genes associated with the UPR transcription factor X-box binding protein 1 (XBP1) including BCL2, the proapoptotic BCL2-interacting Killer (BIK) and the Nuclear Factor Kappa B (NF-κB)." (PMID 37444574, 2023). "Likewise, the TUT1 down-regulation in breast cancer negatively influences the stability of the pro-apoptotic factor BCL-2-interacting-killer (BIK), also acting as a tumor suppressor." (PMID 33430133, 2021).
breast carcinoma (continued). "LncRNA H19 could promote drug resistance in HR+ breast cancer cells through inhibiting BIK and NOXA expression." (PMID 34938660, 2021). "In order to interrogate these results at the level of BIK protein, we analyzed whether BIK protein levels predicted relapse in ER-positive breast cancer patients differently than in ER-negative patients (n = 152)." (PMID 32528057, 2020). "It was unclear whether BIK promotes or suppresses tumor survival within the context of breast cancer." (PMID 32528057, 2020). "High levels of BIK in breast cancer tumors are prognostic for poor patient outcomes." (PMID 32528057, 2020). "Thus BIK-mediated inefficient apoptosis facilitates cellular evolution and identifies a potential new molecular mechanism for recurrence in a subset of breast cancers." (PMID 32528057, 2020). "Inspired by that, TPD52 is a well-known oncogene overexpressed in breast cancer, we sought to determine whether regulation between Star-PAP and TPD52 was also involved in breast cancer development besides BIK." (PMID 31649118, 2019). "We previously confirmed that H19 inhibits transcription of BIK and NOXA in breast cancer, however, the underlying mechanism is still unknown." (PMID 27845892, 2016). "ii) It has been proposed that GRP78 may bind to BIK through its BH-3 domain, which reverses the increased BIK expression in breast cancer that results from the presence of anti-estrogen agents, disrupting BIK/BCL-2 complex formation." (PMID 26622781, 2015). "We have previously reported that in breast cancer cell lines, the induction of BIK by 3D COL1 is observed in the non-invasive cell lines, which retain epithelial features, while the invasive mesenchymal-like cell lines, which underwent an epithelial-to-mesenchymal transition, are resistant." (PMID 25774665, 2015). "The expression of BIK is known to have prognostic significance in breast cancer." (PMID 24489730, 2014). "Thus, BIK predicted recurrence and mortality in ER-positive breast cancer cohorts, suggesting that BIK-mediated sublethal apoptosis may contribute to clinical tumor evolution specifically in this subset of breast cancers." (PMID 32528057, 2020). "In accordance with this hypothesis, the enforced expression of MT1-MMP in luminal-like breast carcinoma cells abrogates the BIK-mediated apoptosis, suggesting that the degradation of type I collagen could be responsible of a lower DDR1 activation and thus a decreased apoptosis." (PMID 31130862, 2019). "Bcl2-interacting killer (BIK), a major member of the BH3-only Bcl-2 family, is an unfavorable prognostic marker for breast cancer." (PMID 34517787, 2021). "In fact, type I collagen can activate DDR1 to induce the expression of BIK, a pro-apoptotic member of the BCL-2 protein family, thereby triggering apoptotic cell death in these breast cancer cell lines." (PMID 32582700, 2020). "In a previous study, we have examined this correlation in multiple breast cancer cell lines, by analyzing expression levels of E-cadherin, vimentin, DDR1, DDR2, MT1-MMP, and BIK mRNAs in 58 breast cancer cell lines." (PMID 31130862, 2019). "In contrast, the more mesenchymal breast cancer cell lines (E-cadherin-low and vimentin-high) were characterized by a weak DDR1 level, a high MT1-MMP, and a low BIK expression." (PMID 31130862, 2019). "By regulating BIK expression, Star-PAP induced apoptosis of cancer cells through the mitochondrial pathway, inhibited progression of breast cancer and sensitized breast tumors to chemotherapeutic drugs." (PMID 28151486, 2017). "Ectopic expression of Star-PAP inhibited the proliferation of breast cancer cells, and Star-PAP induced the mitochondrial apoptosis through regulating the expression of BIK (BCL2-interacting killer)." (PMID 28151486, 2017). "We revealed that by regulating the expression of BIK, Star-PAP acquires the ability to inhibit growth of breast cancer cells through the mitochondrial apoptosis pathway." (PMID 28151486, 2017).
breast carcinoma (continued). "These overexpression and knockdown studies all validated BIK and NOXA as important downstream targets of H19, and confirmed a strong involvement of both genes in the H19-mediated PTX resistance of breast cancer cells." (PMID 27845892, 2016). "Inhibition of BIK and NOXA by H19 reduced apoptosis in breast cancer cells and their subsequent sensitivity to drugs." (PMID 27845892, 2016). "Following this confirmation of BIK and NOXA as targets of H19, we evaluated their roles in the drug resistance of breast cancer cells by restoring the expression of BIK and NOXA in MCF-7R cells." (PMID 27845892, 2016). "Restoration of BIK expression by removal of epigenetic markers via inhibition of these lncRNAs or by DNA methyltransferases (DNMTs) / Histone methyltransferases (HMTs) inhibitors could therefore represent a potential therapeutic strategy for treatment of refractory breast cancer." (PMID 27845892, 2016). "The expression levels of E-cadherin, vimentin, DDR1, DDR2, α2 integrin, α11 integrin, COL1A1, MT1-MMP, BIK, estrogen receptor α, progesterone receptor, and HER2 mRNAs in 58 breast cancer cell lines were analyzed in silico, by using the Broad-Novartis Cancer Cell Line Encyclopedia (CCLE) database." (PMID 31130862, 2019). "Our recent study found that Star-PAP is downregulated in breast cancer cells, and the overexpression of Star-PAP induced cell apoptosis and inhibited proliferation partly through upregulating BIK expression, suggesting that Star-PAP functions as a tumor suppressor." (PMID 31649118, 2019). "Data showed that overexpression of DDR1 induced a decrease in cell growth and an increase in BIK expression, suggesting that moderate expression level of full length DDR1 in basal-like breast carcinoma provides them with a capacity to resist to collagen-induced cell growth suppression and apoptosis." (PMID 31130862, 2019). "In human breast cancer cells, high levels of GRP78 confer resistance to estrogen starvation-induced apoptosis via an inhibition of the BCL2-interacting killer (BIK), a pro-apoptotic BH3-only protein, and the induction of three anti-apoptotic molecules: B-cell lymphomas BCL2, BCL-XL, and BCL-W." (PMID 29932125, 2018). "Moreover, by regulating the expression of BIK (BCL2-interacting killer), Star-PAP induced apoptosis of breast cancer cells through the mitochondrial pathway." (PMID 28151486, 2017). "Therefore, in breast cancer cells, the apoptosis induced by Star-PAP overexpression is dependent on BIK." (PMID 28151486, 2017). "Thus, irrespective of the nature of the stress, BIK upregulation has the potential to drive tumor aggression in breast cancers." (PMID 32528057, 2020).
prostate carcinoma (11 papers, 2016 to 2025). A carcinoma that arises from epithelial cells of the prostate gland. "Two recently published studies identified several genes—BIK, SAMHD1, FAM111A, AOX1, among others—in which rare variants are significantly and strongly associated with increased risk of prostate cancer (PCa) and its aggressiveness." (PMID 40825105, 2025). "Consistently, our data showed that BIK was increased in response to cisplatin treatment and we found that KLF4 upregulated the expression of BIK in prostate cancer cells and promoted cisplatin-induced BIK expression." (PMID 30176890, 2018). "In our study, MLN4924 caused accumulation of WEE1/p21/p27, CDT1/ORC1 and NOXA/BIK, which were associated with MLN4924-IR-enhanced G2 cell-cycle arrest, DNA damage and apoptosis in prostate cancer cells." (PMID 27224919, 2016). "In addition to TERT, we found rare non-synonymous variants in three genes associated with decreased prostate cancer risk (ANO7, SPDL1 and AR), and three genes associated with increased risk (HOXB13, CHEK2 and BIK)." (PMID 39971927, 2025). "Similarly, we found that KLF4 was induced by cisplatin and that elevated KLF4 promoted prostate cancer cell apoptosis via transcriptionally upregulating BIK expression." (PMID 30176890, 2018). "In prostate cancer, miR-32-5p regulates the expression of BCL-2-interacting killer (BIK), a proapoptotic protein belonging to the BCL-2 family, and induces resistance to cisplatin-induced apoptosis." (PMID 33406670, 2021). "KLF4 positively regulates the expression of miR-1, BCL2-interacting killer (BIK) and insulin-like growth factor 2 (IGF2) in prostate cancer." (PMID 33266506, 2020). "Our recent studies have indicated that KLF4 upregulates MGLL and BIK in HCC and prostate cancer cells." (PMID 30658712, 2019). "The expression of both pro-apoptotic (BAX,BIK, and BAD) and anti-apoptotic genes(MCL-1 and BCL-XL) was not affected byBAP1-knockdown in prostate cancer cells." (PMID 32422649, 2020).
non-small cell lung carcinoma (5 papers, 2016 to 2022). A group of at least three distinct histological types of lung cancer, including non-small cell squamous cell carcinoma, adenocarcinoma, and large cell carcinoma. "Previous studies confirmed that SNHG17 promoted cell proliferation and migration by regulating FOXA1, XF1 and BIK expression in non-small cell lung cancer." (PMID 32351538, 2020).
ovarian carcinoma (5 papers, 2016 to 2022). A malignant neoplasm originating from the surface ovarian epithelium. "High expression of RBP LARP1 co-associates with BCL2 and BIK in BCL2 messenger ribonucleoprotein (mRNP) complexes in epithelial ovarian cancer and stabilizes BCL2 while destabilizing BIK, which promotes ovarian cancer cell survival and leads to adverse prognosis." (PMID 33643390, 2021). "For example, LARP1 enhances the stability of BCL2 but attenuates the stability of BIK, leading to the malignant progression of ovarian cancer." (PMID 34890108, 2022). "The RBP ribonucleoprotein 1, translational regulator 1 (LARP1) promotes ovarian cancer progression and by altering the stability of its target mRNAs B cell lymphoma 2 (BCL2) and BCL-2–interacting killer (BIK)." (PMID 33193718, 2020). "To confirm LARP1 protein interacts with BCL2 and BIK mRNAs, as suggested by the published LARP1 interactome, we performed RNA-immunoprecipitation in OVCAR8 and SKOV3 ovarian cancer cell lines." (PMID 26717985, 2016). "We hypothesized that, as LARP1 acted as a post-transcriptional regulator of the apoptosis players BCL2 and BIK, modulation of LARP1 expression in ovarian cancer cells would affect their survival." (PMID 26717985, 2016). "To determine whether LARP1 could be regulating the stability of BCL2 and BIK transcripts in patient tumours, we evaluated trends in LARP1, BCL2 and BIK transcript abundance in the TCGA ovarian cancer dataset." (PMID 26717985, 2016).
viral infection (4 papers, 2013 to 2025). "A previous study showed that knockdown of BIK in human airway epithelial cells significantly reduced the apoptosis induced by influenza A virus infection, suggesting that BIK is a major mediator for the apoptotic pathway triggered by viral infection." (PMID 40434097, 2025). "BIK initiates apoptotic responses to genotoxic stress or disruption of host cell protein synthesis in processes like viral infections or treatment with proteasomal or protein synthesis inhibitors." (PMID 23922782, 2013). "BIK is a critical effector in apoptosis that is induced by toxins, cytokines, and virus infection." (PMID 35008922, 2022).
B cell lymphomas (3 papers, 2016 to 2018). "Although mutations in BIK have been found in B-cell lymphomas, little is known about the role of BIK in hematopoietic malignancies." (PMID 27902785, 2016). "However, somatic missense mutations have been observed in BIK in B cell lymphomas in humans, including FL, marginal zone (MZL), and DLBCL, suggesting that its loss may contribute to these lymphomas." (PMID 30671383, 2018). "We have shown that the BIK expression significantly correlated with TCF3 in normal B cell subtypes and B cell lymphomas." (PMID 27166193, 2016).
breast tumors (3 papers, 2017 to 2020). "We therefore first assessed BIK protein levels from snap-frozen primary breast tumor samples and observed that the majority (~80%) of the samples had detectable BIK levels of differing intensity." (PMID 32528057, 2020). "The expression level of apoptosis marker BIK was positively correlated to that of DDR1 in basal-like breast tumors (r = 0.2251, p = 0.0258)." (PMID 31130862, 2019). "This agrees with the positive correlation observed between DDR1 and BIK expression in human basal-like breast tumors." (PMID 31130862, 2019). "It is worth noting that the mRNA level of the pro-apoptotic mediator BIK was positively correlated to that of DDR1 in human basal-like breast tumors." (PMID 31130862, 2019).
colon cancer (3 papers, 2017 to 2022). "show that BRAF V600E mutation may induce the expression of PD-L1 and then increase chemotherapy-induced apoptosis by inducing BIM and BIK proteins in colon cancer." (PMID 35619907, 2022). "Elevated BIK promoted cisplatin and UV-induced mitochondrial apoptosis in colon cancer cells." (PMID 30176890, 2018).
colorectal cancer (3 papers, 2017 to 2025). A primary or metastatic malignant neoplasm that affects the colon or rectum. "In a study of rectal cancer, BIK was also identified as a poor prognostic marker for microsatellite-stabilized colorectal cancer harboring KRAS mutations, and rectal cancer patients with high expression of BIK tended to have shorter survival times." (PMID 40438322, 2025). "BH3-only protein BIK has been shown to act as a tumor suppressor and deletions in 22q13.2 and 22q13.3 chromosomal regions containing the Bik locushave been reported in colorectal cancers, head and neck cancers, gliomas and renal cell carcinomas." (PMID 28796811, 2017).
lung carcinoma (3 papers, 2016 to 2023). "BIK is a member of the BCL-2 family and is considered as a tumor suppressor due to its vital function in promoting apoptosis including lung cancer." (PMID 35371316, 2022).